ATM (ATM serine/threonine kinase)
Diseases named in the same sentence as ATM in open-access papers (continued):
Sharing a sentence is not in itself a finding about the gene and the disease.
breast cancer (continued). "Based on our findings, there was a significant increase in the expression levels of phosphorylated histone H2A.X, ATM, CHK1, CHK2, and BRCA1 in both breast cancer cell lines which suggested that ATM acts as the key regulator in 6-gingerol-induced DDR." (PMID 33925065, 2021). "In summary, our study defined ATM and CHEK2 as moderate risk genes for breast cancer in Chinese women." (PMID 34606182, 2021). "In particular, the mutation frequency for ATM is 0.78% and for CHEK2 1.08% in unselected breast cancer patients, whereas the prevalence in unaffected women is 0.41% for ATM and 0.42% for CHEK2." (PMID 33919281, 2021). "Another study reported one deletion 1563delAG and one insertion 2572insT in ATM gene among 190 breast cancer patients." (PMID 34493284, 2021). "Another study indicathat ATM mutations and BRCA1 mutations are associated with breast cancer patients." (PMID 34493284, 2021). "Histological analyses of breast cancer subtypes showed that there were varying trends between ATM and CHEK2." (PMID 35008774, 2021). "At present, the discussion regarding the ATM gene is of great value in the diagnosis, treatment, and prognosis of breast cancer." (PMID 34198652, 2021). "In line with this, an inverse correlation between Notch and pATM has been found in breast cancer, and Notch inhibition results in increased radiation sensitivity in an ATM-dependent manner." (PMID 33968932, 2021). "This study classified ATM, BARD1, CHEK2, and RAD51D as moderate risk breast cancer susceptibility genes in Chinese women." (PMID 34606182, 2021). "A case–control study found evidence for an independent association of PC risk with PGVs in six genes: ATM, BRCA1, BRCA2, CDKN2A, MLH1, and TP5316, five of which (excluding CDKN2A) have a clear link to breast cancer risk." (PMID 34127761, 2021). "For the clinical management of GPV carriers of ATM, CHEK2, or BARD1, all of which are autosomal dominant, it is recommended to perform imaging screenings for preventive risk management against breast cancer." (PMID 35008774, 2021). "Among different variants, isubstitutions are the most common, and there is an association between ATM variants and BRCA mutations in breast cancer incidence." (PMID 34493284, 2021). "ATM gene mRNA and ATM protein levels are independent prognostic factors for sporadic breast cancer and play a good guiding role in treatment." (PMID 34198652, 2021). "ATM (ataxia telangiectasia mutated) has been reported to trigger a cascade of signalling reactions mediating phosphorylation of Akt, GSK3ß and Snail to promote EMT in breast cancer cells." (PMID 33289330, 2021). "ATM and CHEK2 are recognized as the most common breast cancer susceptibility genes, and their attenuation is associated with BRCAness, namely phenocopies of BRCA1/2 defects." (PMID 35008774, 2021). "It was reported that ATM gene expression decreased in breast cancer tissues and cells compared to controls." (PMID 34493284, 2021). "Biallelic carriers of PVs in other, dominant breast cancer susceptibility genes such as BRCA2, ATM, PALB2, and NBN are known to have more severe cancer phenotypes than monoallelic carriers." (PMID 31993860, 2020).
breast cancer (continued). "In a previous study of breast cancer patients, those with ATM rs664677 TC genotype showed increased radiation resistance compared to the rs664677 TT genotype." (PMID 32329754, 2020). "This activation is induced and maintained by overexpressed ZEB1 recruiting the transcriptional coactivators p300/PCAF to the ATM promoter, which results in the chemoresistance of breast cancer cells." (PMID 32266287, 2020). "We notice that another critical signal pathway in breast cancer, ATM Signaling Network in Development and Disease (P = 0.000321, q = 0.0318), is also regulated by PRR14 in the result of the over-representation analysis." (PMID 32541902, 2020). "It is worth noting that the ovarian cancer patients harbouring ATM PV, as well as the breast cancer cases with CHEK2 PV, present a familial history matching both HNPCC and HBOC criteria." (PMID 32522261, 2020). "Other studies using multigene panels found that over 4% of women at risk of hereditary breast cancer had mutations in genes other than BRCA1/2, including PALB2, CHEK2, and ATM." (PMID 32090079, 2020). "It was also shown that inhibitors for the DNA repair kinases ataxia telangiectasia mutated (ATM) and DNA-PK restored doxorubicin-induced apoptosis in doxorubicin-resistant APC-deficient breast cancer cells." (PMID 33105836, 2020). "In CD44+/CD24- cell lines and the primary culture of patient breast cancer cells, elevation in both expression and phosphorylation of ATM were found." (PMID 33680952, 2020). "Among these 37 cases, 35 had breast cancer and 2 (ATM p.R805* and RAD51D p.K111fs) had ovarian cancer 13,15." (PMID 32566746, 2020). "Meanwhile, in some colorectal cancer, cervical cancer and breast cancer cell lines, quercetin acted as a radiosensitizer by blocking ATM activation and its downstream signaling, thereby prolonging the persistence of damage and inducing apoptosis." (PMID 33330091, 2020). "Several mutations, including those in BRCA1, BRCA2, ATM, CHEK2, and PALB2, have been associated with the clinicopathological features exemplified by the breast cancer subtype and tissue of origin for additional cancers." (PMID 32566746, 2020). "Valencia-González and colleagues also revealed that there was a significant expression of activated ATM only in the CSCs from Hela and human breast cancer MCF-7 cells, suggesting that phosphorylated ATM plays critical roles in breast cancer stem cells." (PMID 32566127, 2020). "Other studies have confirmed the importance of ATM in maintaining the stemness of breast cancer cells, albeit through different mechanisms." (PMID 32566127, 2020). "ATM expression was useful to stratify the low Ki67 group into prognostic subgroups in patients with breast cancer." (PMID 33224881, 2020). "Meanwhile, numerous studies have associated mutations in moderate-penetrance genes, including PALB2, ATM, CHEK2, BRIP1, with increased breast cancer risk of two to four-fold compared to the 10% risk of the general population." (PMID 32091409, 2020). "To date, multiple breast cancer predisposition genes have been identified, mainly from studies of women of European ancestry, including BRCA1, BRCA2, PALB2, CHEK2, and ATM, which together accounted for 25% of the familial risk." (PMID 32318955, 2020). "A key player in HR, ataxia telangiectasia mutated (ATM), was downregulated by miR-18a in breast cancer, miR-26a in glioma and miR-421 in squamous cell carcinoma (SCC)." (PMID 32585857, 2020). "Tumours with low ATM or high ATR levels in conjunction with MYC overexpression also have worse overall breast cancer-specific survival (BCSS) (p value < 0.05)." (PMID 30746633, 2019).
breast cancer (continued). "They detected significant associations of some haplotypes of BABAM1, ATM, CTIP (RBBP8), TOPBP1, BRIP1, BRE and RAD50 with the modification of breast cancer risk." (PMID 30823486, 2019). "Reported DSB repair variants in breast cancer comprise PALB2, NBN, RAD51, ATM, CHEK2, ATR, RAD50, and WRN." (PMID 31658756, 2019). "In the present study we assessed the role of ATM rs1801516 as predictive factor for fibrosis and telangiectasia in a cohort of breast cancer patients who received radiotherapy after breast conserving surgery." (PMID 31756226, 2019). "In the present study, we assessed the role of ATM rs1801516 as risk factor for radiation-induced fibrosis and telangiectasia, using the LENT-SOMA scoring scale in 285 breast cancer patients who received radiotherapy after breast conserving surgery." (PMID 31756226, 2019). "The National Comprehensive Cancer Network (NCCN) guidelines for genetic assessment in hereditary breast cancer (version 3.2019) recommends genetic evaluation of ATM, CDH1, CHEK2, NBN, NF1, and PALB2 in addition to BRCA1/2 genes." (PMID 31658756, 2019). "In ER+ breast cancer, similarly, MYC overexpressed tumours with low ATM levels were associated with worse survival (p < 0.001) including in patients who received endocrine therapy." (PMID 30746633, 2019). "For example, a reduced DNA damage response capacity was observed in lymphomas of Golden retriever dogs, and a lower expression of the ATM serine/threonine kinase (ATM) gene was found in canine mammary tumors." (PMID 31681409, 2019). "High rates of genomic mutations in DNA damage repair (DDR) genes, such as breast cancer 2, early onset (BRCA2) and ataxia telangiectasia mutated (ATM) genes, have been detected in multiple malignancies." (PMID 31060606, 2019). "Overall, these findings suggest that there is still insufficient evidence to draw definitive conclusions on the correlation between ATM rs1801516 and late radiation skin injuries in breast cancer patients." (PMID 31756226, 2019). "Germline pathogenic variants in DNA repair genes BRCA1, BRCA2, PALB2, ATM, and CHEK2 are associated with breast cancer risk." (PMID 31700994, 2019). "One study of over 94,000 women with breast cancer and 75,000 controls found that women in the highest 1% of a 313 SNV PRS had a lifetime risk of 32.6%, well above that of PVs in genes such as ATM and CHEK2." (PMID 30832243, 2019). "We then proceeded to investigate MYC, ATR and ATM protein levels in clinical breast carcinoma samples." (PMID 30746633, 2019). "Leveraging these RPPA ATM protein levels, we expanded our analysis to all TCGA breast cancer patients, and found ATM levels remained strongly predictive of CTL score." (PMID 29615613, 2018). "We then substantiated ZEB1-regulated expression of ATM at mRNA and protein levels and in human breast cancer." (PMID 29352223, 2018).
breast cancer (continued). "Phosphorylated ATM offered strong predictive value both in the CPTAC breast cancer patient cohort, as well as in a pre-clinical murine syngeneic transplant model." (PMID 29615613, 2018). "There are some indications of a potential contribution of other genes involved in the DNA damage response to breast cancer risk, including NBS1, ATM, H2AFX, BRIP1, BARD1, RAD51C and RAD51D." (PMID 29678143, 2018). "Taken together, we have found an important mechanism that ZEB1 regulates the sensitivity of breast cancer cells to genotoxic drug treatment in an ATM-dependent manner." (PMID 29352223, 2018). "Mutations in ATM, BRCA2, and PALB2 were also more frequent in patients with PC with a family history of breast cancer (first- or second-degree relative)." (PMID 31497750, 2018). "In this case-control study, we investigated the relationships between other variants in ATM, H2AFX and MRE11 genes and risk of breast cancer." (PMID 29678143, 2018). "Consistent with our observations in breast cancer, this relationship appeared to be functional, as genetic ATM inactivation abrogated the correlation between ATM protein levels and CTL score/cytokine gene expression in the gastric cancer cohort." (PMID 29615613, 2018). "Here we note that ATM and CHEK2 have recently been added to NCCN’s list of genes with associated medical action for breast cancer." (PMID 29945567, 2018). "A more intermediate risk of developing breast cancer is conferred by germline mutations in the genes CHEK2, ATM, PALB2, and NBS1, which are, in the general population, more prevalent than mutations in the high risk breast cancer genes." (PMID 30116257, 2018). "In five patients (5 of 83; 6% of cohort), we detected causative pathogenic variants in established hereditary breast cancer susceptibility genes (i.e., PALB2, CHEK2, ATM)." (PMID 30086788, 2018). "In consistency with our results, other studies have shown that ATM/RB1 inactivation were associated with poor prognosis in multiple cancer types, such as leukemia, breast cancer, lung cancer, brain tumor and bladder cancer." (PMID 29682192, 2018). "MiR-18a is upregulated in breast cancer cell lines and patient tissues, interestingly its ectopic expression downregulates ATM." (PMID 30234015, 2018). "To determine the correlation between ZEB1 and ATM expression in human breast cancer, we performed immunohistochemical staining in 139 cases of primary breast carcinoma." (PMID 29352223, 2018). "Four SNPs [rs3218550 (XRCC2), rs6917 (PHB), rs1801516 (ATM), and rs13689 (CDH1)] were significantly associated with risk of breast cancer." (PMID 29433565, 2018). "(B) SALL1 expression in breast cancer cells induced expression of phosphorylated active of ATM in the transfected cells." (PMID 29625565, 2018). "Treatment of MCF-7, MDA and E0771 breast cancer cells with KU55933 dramatically suppressed the phosphorylation of ATM in SALL1-transfected tumor cells and prevented induction of senescence in tumor cells." (PMID 29625565, 2018). "Third, ZEB1 promotes DDR in breast cancer cells in response to chemotherapy and confers chemoresistance by reducing genotoxic drug-induced DSBs in an ATM-dependent manner." (PMID 29352223, 2018). "After radiation, CD44+/CD24− BCSCs isolated from established breast cancer cell lines and primary culture of patient breast cancer cells presented high ATM signaling activity, and treatment with an ATM inhibitor resensitized these cells to radiation." (PMID 30200262, 2018). "The second carrier of an ATM frameshift mutation (OCL56) was diagnosed at 73, and had a family history of OVCA (two additional cases besides herself) as well as two cases of breast cancer, all on the maternal side." (PMID 28591191, 2017).
breast cancer (continued). "Herein, we utilised the preparation of 3D spheroid cultures, also known as “mammospheres”, as functional assay to enrich for a population of cells with a stem-like phenotype to investigate the role of ATM in the regulation of Breast Cancer Stem-like cells." (PMID 28423511, 2017). "Somatic mutations and their role in breast cancer disposition have been revealed in earlier breast cancer related studies and it is also found that genes like ATM, PTEN, etc. play major role in several germline point mutations." (PMID 28477017, 2017). "Other potential sources of DNA repair deficiency in breast cancer, also involving DSB repair processes, include germline mutations in DNA repair genes PALB2, FANCM, ATM, CHEK2 (and possibly also RAD51C) characterized as loss-of-function variants." (PMID 28679371, 2017). "Highlighting ATM expression showed a significant positive correlation with the expression of autophagic gene ATG4C among microarray data derived from 511 breast cancer samples." (PMID 28423511, 2017). "Multiple studies have also demonstrated that genes such as ATM and CHEK2 are associated with increased breast cancer risk." (PMID 29093764, 2017). "We detected pathogenic mutations in nine of the 99 women in this group involving the ATM, BRCA1, CDH1, and CHEK2 genes, all of which have been associated with an increased risk of bilateral breast cancer in the previous studies." (PMID 28281021, 2017). "One patient with an ATM pathogenic variant in our sample (OCF28-1) had a family history of liver, lung (n = 2) and breast cancer, on the same parental side of the family." (PMID 28591191, 2017). "Further association studies, in families and in the general population, are needed to confirm the association of genes such as ATM and PALB2 with MBC and to calculate more precise breast cancer risks for males with pathogenic variants in these genes." (PMID 28008555, 2017). "Known genetic factors contributing to a higher lifetime risk of breast cancer comprise rare variants in BRCA1, BRCA2, PALB2, ATM and CHEK2." (PMID 28199975, 2017). "We previously demonstrated that ATM promotes HER2-dependent tumorigenesis in breast cancer, reporting also a context-dependent role of ATM targeting in cancer." (PMID 28423511, 2017). "We have recently identified ATM as a promoter of HER2 tumorigenicity in breast cancer, suggesting a dual function of ATM in cancer." (PMID 28423511, 2017). "In the present study, using KU55933 to reduce the level of phospho-ATM sensitized breast cancer cell lines to Olaparib." (PMID 27613518, 2016). "Overall, in our present study we confirmed that inhibiting ATM increased cytotoxicity of PARP inhibitor in breast cancer cell lines, and demonstrated for the first time that depleting 53BP1 reduced this cytotoxicity." (PMID 27613518, 2016). "Phospho-ATM and 53BP1 protein expressions were determined in human breast cancer tissues by immunohistochemistry (IHC)." (PMID 27613518, 2016). "Taken together, these data indicate that miR-302b, by targeting E2F1, negatively affects ATM expression levels in breast cancer cells of different origin." (PMID 26623722, 2016). "miR-302b has been reported to enhance breast cancer cell sensitivity to cisplatin by regulating ATM, which is an important serine/threonine kinase that transduces DNA damage signals to downstream effectors in the DNA damage response." (PMID 27405111, 2016). "Another group performed a meta-analysis using ATM sequence data from 1544 breast cancer cases and 1224 controls." (PMID 27716388, 2016).